GALNT2 (polypeptide N-acetylgalactosaminyltransferase 2)
Description:
Catalyzes the initial reaction in O-linked oligosaccharide biosynthesis, the transfer of an N-acetyl-D-galactosamine residue to a serine or threonine residue on the protein receptor. Has a broad spectrum of substrates for peptides such as EA2, Muc5AC, Muc1a, Muc1b. Probably involved in O-linked glycosylation of the immunoglobulin A1 (IgA1) hinge region. Involved in O-linked glycosylation of APOC-III, ANGPTL3 and PLTP. It participates in the regulation of HDL-C metabolism.
Synonyms: GalNAc-T2; CDG2T
Tractability: Small molecule: a structure with a bound ligand is known; a high-quality ligand is known; it has a high-quality binding pocket. Antibody: UniProt places it where antibodies can reach, with high confidence; UniProt predicts a signal peptide or a membrane-spanning region; its Gene Ontology location is reachable by antibodies, with medium confidence. PROTAC: ubiquitination databases record sites on it; its protein half-life has been measured; a small molecule that binds it is known.
Target class: Enzyme; Transferase
Safety:
Unwanted effects reported when the protein is acted on. In parentheses: how it was acted on, where the effect was seen, and who reports it.
reduction in HDL-C (source: ClinPGx)
Gene: Protein-coding gene on chromosome 1 (230,057,990 to 230,282,128, forward strand). Ensembl gene ENSG00000143641.
Subcellular location: Golgi apparatus, Golgi stack membrane; Secreted
Subcellular location (Human Protein Atlas): Golgi apparatus
Pathways (Reactome):
Metabolism of proteins: O-linked glycosylation of mucins
Vesicle-mediated transport: COPI-independent Golgi-to-ER retrograde traffic
Gene Ontology:
Molecular function: manganese ion binding; polypeptide N-acetylgalactosaminyltransferase activity; protein binding
Biological process: positive regulation of immunoglobulin production; protein maturation; protein O-linked glycosylation; protein O-linked glycosylation via N-acetyl-galactosamine
Cellular component: extracellular region; Golgi apparatus; Golgi stack; membrane; perinuclear region of cytoplasm; endoplasmic reticulum membrane; Golgi membrane; Golgi cisterna membrane
Genetic constraint (gnomAD): Loss-of-function variants: 28 observed, 74.49 expected, observed/expected ratio (o/e) 0.38, 90% interval 0.28 to 0.51. The upper end of that interval is the gene's LOEUF score, 0.51, which puts it in group 2 of 6, group 1 being the genes least tolerant of losing a copy. Missense variants: 604 observed, 745.17 expected, observed/expected ratio (o/e) 0.81, 90% interval 0.76 to 0.87. Synonymous variants: 286 observed, 275.43 expected, observed/expected ratio (o/e) 1.04, 90% interval 0.94 to 1.14.
Gene-disease validity (ClinGen):
ClinGen rates the evidence that GALNT2 causes each of these diseases.
congenital disorder of glycosylation, type iit (autosomal recessive): Strong.
Homologues: Orthologues: chimpanzee GALNT2 (100% identical), macaque GALNT2 (99% identical), rabbit GALNT2 (99% identical), dog GALNT2 (98% identical), rat Galnt2 (96% identical), guinea pig GALNT2 (96% identical), mouse Galnt2 (96% identical), pig GALNT2 (93% identical), tropical clawed frog galnt2 (88% identical), zebrafish galnt2 (85% identical), Drosophila melanogaster Pgant2 (60% identical), Caenorhabditis elegans gly-4 (47% identical). Paralogues in human: GALNT16 (50% identical), GALNT14 (48% identical), GALNT1 (41% identical), GALNT13 (40% identical), GALNT6 (39% identical), GALNT12 (39% identical), GALNT11 (39% identical), GALNT5 (37% identical), GALNT4 (37% identical), GALNT3 (36% identical), GALNT10 (35% identical), GALNT18 (33% identical), and 7 more.
Diseases named in the same sentence as GALNT2 in open-access papers:
GALNT2 is named in the same sentence as 89 diseases in open-access papers, as found by Europe PMC text mining. Sharing a sentence is not in itself a finding about the gene and the disease. The quoted sentences say what the papers report.
hepatocellular carcinoma (12 papers, 2014 to 2023). A malignant tumor that arises from hepatocytes. "For this reason, GALNT2 has been implicated in malignant control in hepatocellular carcinoma through modification of epidermal growth factor receptor (EGFR) glycosylation." (PMID 28025493, 2016). "In our previous studies, downregulation of GALNT2 in hepatocellular carcinoma and neuroblastoma was associated with increased malignancy." (PMID 26848976, 2016). "GALNT2 is associated with lipid levels, insulin signaling, hyperglycemia, and the malignant behavior of hepatocellular carcinoma." (PMID 24906187, 2014). "Our team found that GALNT2 is downregulated in hepatocellular carcinoma (HCC) and its re‐expression suppresses the malignant character of HCC by modifying the O‐glycosylation and activity of EGF receptor." (PMID 36409270, 2023). "After transfection of the GALNT2 gene into hepatocellular carcinoma cells, EGF-induced cell proliferation, migration and invasion were reduced." (PMID 34069424, 2021). "Our previous studies have shown that the activity of EGFR can be modified by GALNT1 and GALNT2 in hepatocellular carcinoma and by GALNT2 in oral squamous cell carcinoma." (PMID 28388560, 2017). "We recently showed that EGFR is decorated with mucin-type O-glycans, and the O-glycans and activity of EGFR can be modified by N-acetylgalactosaminyltransferase 2 (GALNT2) in hepatocellular carcinoma." (PMID 25003232, 2014). "Multiple lines of evidence demonstrated that GALNT2 was dysregulated in several solid tumors, such as glioma, neuroblastoma, gastric adenocarcinoma, oral squamous cell carcinoma, and hepatocellular carcinoma." (PMID 36058918, 2022). "The dysregulation of GALNT2 contributes to the malignant behavior of hepatocellular carcinoma cells, and enhances the motility of oral squamous cell carcinoma, whereas GALNT2 has also been reported to suppress malignant phenotypes in neuroblastoma and gastric adenocarcinoma." (PMID 36110252, 2022). "We have previously shown that dysregulation of GALNT2 contributes to the malignant progression of hepatocellular carcinoma and oral squamous carcinoma cells by modifying glycosylation of the epidermal growth factor receptor, a member of receptor tyrosine kinase (RTK) family." (PMID 26848976, 2016). "Previous studies reported that silencing of GALNT2 could inhibit insulin-induced insulin receptor activation and Akt phosphorylation in hepatoma cells, whereas overexpression of GALNT2 in oral cancer cells could promote EGF-induced phosphorylation of EGFR and Akt." (PMID 32559179, 2020). "GALNT2, sharing a high amino acid sequence homology with GALNT14, regulates the malignant character of hepatocellular carcinoma by modulating the structure of short O-glycans on EGFR." (PMID 28388560, 2017). "Our previous studies showed that GALNT2 modulated EGFR activity and suppressed EGF-induced proliferation, migration, and invasion in hepatocellular carcinoma cells." (PMID 26848976, 2016). "In hepatocellular carcinoma (HCC), we observed that GALNT2 mRNA expression exhibits significant down-regulation in HCC tissues compared with normal counterparts." (PMID 27686492, 2016).
type 2 diabetes (10 papers, 2013 to 2024). "In conclusion, our data indicate for the first time that in type 2 diabetes the expression of GALNT2 is associated with several serum metabolites." (PMID 38627282, 2024). "Our data indicate that in type 2 diabetes the expression of GALNT2 is associated with several serum metabolites." (PMID 38627282, 2024). "The variant rs35498929-T, also in the GALNT2 locus, was associated at a suggestive significance level with decreased apo-CIII0a (p = 7.44 × 10−7) and with higher prevalence of type 2 diabetes (p = 0.006) in the relatively small DiaGene study for such analyses." (PMID 37834292, 2023). "The main finding of our study is that reduced GALNT2 expression in circulating blood cells is associated with type 2 diabetes." (PMID 23894607, 2013). "In conclusion, our data indicate that GALNT2 is down-regulated in patients with type 2 diabetes and suggest that this association is, at least partly, secondary to hyperglycemia." (PMID 23894607, 2013). "Aim of this study was to investigate in type 2 diabetes whether expression level of GALNT2, a positive modulator of insulin sensitivity, is associated with a metabolic signature." (PMID 38627282, 2024). "The GALNT2 locus linked apo-CIII0a and triglyceride levels to prevalent type 2 diabetes." (PMID 37834292, 2023). "Our present finding is perfectly in line with that reporting GALNT2 down-regulation in liver of Goto-Kakizaki diabetic rats, thus pointing to hyperglycemia as a major cause of GALNT2 down-regulation in patients with type 2 diabetes." (PMID 23894607, 2013). "Abnormal O-GalNAc-glycosylation catalyzed by the GALNT family is associated with various human diseases, with particular attention focused on the link between GALNT2 and metabolic disorders, such as obesity, type 2 diabetes, and lipid abnormalities." (PMID 39209927, 2024). "In conclusion, variants of the GALNT2-gene affect apo-CIII O-glycosylation, lipid metabolism, and the risk of type 2 diabetes." (PMID 37834292, 2023). "Pathways through which GALNT2 impairs lipid metabolism and insulin resistance have been partly identified, while those connecting GALNT2 to hyperglycemia/type 2 diabetes and obesity are only scarcely understood." (PMID 35055114, 2022). "Pathways linking GALNT2 to dyslipidemia and insulin resistance have been partly identified, while those for type 2 diabetes and obesity are yet to be understood." (PMID 35055114, 2022). "In particular, two (GALNT2, SNX17) were also suggested to be associated with type 2 diabetes and obesity in previous studies." (PMID 30110382, 2018). "To investigate the role of GALNT2 in human hyperglycemia, we measured GALNT2 mRNA expression levels in peripheral whole blood cells of 84 non-obese and 46 obese non-diabetic individuals as well as of 98 obese patients with type 2 diabetes." (PMID 23894607, 2013). "Our study investigated whether in patients with type 2 diabetes GALNT2 expression is characterized by a specific signature belonging to several metabolite families, including acylcarnitines, amino acids, biogenic amines, glycerophospholipids and sphingolipids." (PMID 38627282, 2024). "Down-regulation of GALNT2 has been observed in obese patients with type 2 diabetes." (PMID 39541108, 2024). "In the last few years, GALNT2 has attracted great attention as a possible player in many human metabolic abnormalities that all share the common ground of insulin resistance, including atherogenic dyslipidemia, type 2 diabetes and obesity." (PMID 35055114, 2022). "Previous studies have revealed that GALNT2 could influence triglyceride levels, and was involved in type 2 diabetes, hypertension, as well as cancers." (PMID 36110252, 2022). "Taken altogether, the data that we have reported here are quite consistent with the contribution of GALNT2 to several highly prevalent metabolic abnormalities sharing the common ground of insulin resistance, namely atherogenic dyslipidemia, type 2 diabetes and obesity." (PMID 35055114, 2022).
type 2 diabetes (continued). "In all, several studies both in humans and animal models point to GALNT2 as a contributing molecule to highly prevalent metabolic abnormalities, including atherogenic dyslipidemia, type 2 diabetes and obesity, which all impose a heavy burden for patients, their families and society as a whole." (PMID 35055114, 2022). "In addition, several data from both humans and animal models consistently demonstrated the contribution of GALNT2 to several highly prevalent metabolic abnormalities related to insulin resistance, namely atherogenic dyslipidemia, type 2 diabetes, obesity and polycystic ovary syndrome." (PMID 38627282, 2024). "Studies in human PWBC show that GALNT2 levels are reduced in obese patients with type 2 diabetes as compared to obese patients with no diabetes and even more to non-obese control individuals." (PMID 35055114, 2022). "GALNT2 expression levels were measured in PWBC of 84 non-obese non-diabetic individuals, 46 obese non-diabetic individuals and 98 obese patients with type 2 diabetes." (PMID 23894607, 2013). "GALNT2 mRNA levels, as normalized for GAPDH expression, were progressively reduced from non-obese non-diabetic individuals, to obese non-diabetic individuals and to obese patients with type 2 diabetes (p for trend <0.001)." (PMID 23894607, 2013).
dyslipidemia (8 papers, 2009 to 2025). "To date, however, the association of GALNT2 with metabolic syndrome, developmental delay and reduced body weight have not been mechanistically investigated." (PMID 35304331, 2022). "The polypeptide N-acetylgalactosaminyltransferase 2 gene (GALNT2) is a risk locus discovered for dyslipidemia." (PMID 35885984, 2022). "were the first to show an association between GALNT2 genetic variants and metabolic syndrome." (PMID 35304331, 2022). "GALNT2 is confirmed further as a potential link connecting lipid metabolism and obesity and has the potential to be a drug target for treating obesity and dyslipidemia." (PMID 35885984, 2022). "Among these genes, four of them, SORT1, FADS1, FADS2 and GALNT2, are recently reported as candidate genes at highly replicated genetic loci contributing to polygenic dyslipidemia." (PMID 20019805, 2009). "Understanding whether different degrees of changes in GALNT2 modulate different serum lipid fractions can make GALNT2 a target for treating atherogenic dyslipidemia and related clinical events." (PMID 35885984, 2022). "Interestingly, four of the top five significant genes (GALNT2, SNX17, CETP, LIPC) were regarded as dyslipidemia associated genes in the original GWAS study." (PMID 30110382, 2018). "Further support to a role of GALNT2 as a mediator of intermediate metabolism comes from studies showing that genetic variability at the GALNT2 locus is associated with HDL-c and triglycerides levels, two main components of the insulin resistance/metabolic syndrome." (PMID 23894607, 2013).
glioma (7 papers, 2021 to 2024). A benign or malignant brain and spinal cord tumor that arises from glial cells (astrocytes, oligodendrocytes, ependymal cells). "GALNT2 mRNA expression was abnormally increased in IDH1 wild-type gliomas compared with the mutated gliomas." (PMID 37000153, 2023). "The reason why N‐acetylgalactosaminyltransferase 2 (GALNT2) was closely associated with the migration and invasion of glioma cells is that GALNT2 facilitated the malignant features of gliomas by affecting the O‐glycosylation, EGFR phosphorylation, and subsequently the downstream PI3K/Akt/mTOR axis." (PMID 37786890, 2022). "In a functional context, inhibiting GALNT2 disrupts the growth, self-renewal, and aggressive behavior of glioma stem-like cells, primarily by downregulating CD44 expression." (PMID 38596689, 2024). "To decode the expression profile and the potential clinical implications of GALNT2 in glioma, we analyzed RNA-sequencing data of glioma from the TCGA database." (PMID 37000153, 2023). "In this study, we first defined that GALNT2 expression was high in GBM, GSCs, and IDH1 wildtype gliomas, and elevated GALNT2 expression was also associated with unfavorable GBM patients’ clinical outcomes." (PMID 37000153, 2023). "Overall, GALNT2 facilitates the malignant characteristics of glioma by influencing the O-glycosylation and phosphorylation of EGFR and the subsequent downstream PI3K/Akt/mTOR axis." (PMID 35935338, 2022). "GALNT2 knockdown and overexpression in glioma cells demonstrated that GALNT2 was related to cell proliferation, migration and invasion through the EGFR/PI3K/AKT/mTOR signaling pathway." (PMID 34069424, 2021). "We next explore the role of GALNT2 expression in glioma tumorigenesis and malignant invasion." (PMID 37000153, 2023). "Additionally, there was a significant correlation between elevated GALNT2 expression in glioma patients and overall poor survival." (PMID 37000153, 2023). "It was suggested that GALNT2 modulated the O-glycosylation of EGFR in glioma." (PMID 36058918, 2022). "Tumors grown in nude mice were less aggressive when GALNT2 expression was reduced in glioma cells." (PMID 34069424, 2021). "Therefore, GALNT2 may serve as a novel biomarker and a potential target for future therapy of glioma." (PMID 35935338, 2022). "Compared with low-grade glioma patients (WHO grade II and grade III), GBM patients (WHO IV) group exhibited the highest GALNT2 mRNA expression, and GALNT2 mRNA expression level was highly related to patients’ grades." (PMID 37000153, 2023). "In this study, we reveal that polypeptide N-acetylgalactosaminyltransferase 5 (GALNT2) expression level was elevated in GBM, IDH1 wildtype glioma, and GBM stem cells (GSCs)." (PMID 37000153, 2023). "Hence GALNT2 may serve as a potential target of action to treat glioma in the future." (PMID 37786890, 2022). "Thus, GALNT2 knockout decreases the level of phosphorylated EGFR, which could improve the malignant characteristics of glioma." (PMID 37786890, 2022).
neuroblastoma (7 papers, 2014 to 2022). Neuroblastoma (NB) is the most common solid, extracranial childhood tumor. "GALNT2 is expressed differentially in nervous tissues during mouse embryogenesis; however, the role of GALNT2 in neuroblastoma (NB) remains unclear." (PMID 25362349, 2014). "Overexpression of GALNT2 inhibited IGF-l-stimulated growth, migration, and invasion of neuroblastoma cells." (PMID 29970122, 2018).
Obesity (7 papers, 2016 to 2024). Accumulation of substantial excess body fat. "Historically identified as a member of the glycosyltransferase family, GALNT2 was found to modulate adipogenesis and insulin signaling in adipocytes, impacting metabolic processes associated with obesity and diabetes." (PMID 38596689, 2024). "Our study demonstrates the association of the GALNT2 rs4846914_G allele with an increased risk of obesity at an odds ratio of 1.47 (CI: 1.04–2.05)." (PMID 35885984, 2022). "Given that obesity, diabetes, and lipid profiles are inter-connected, we aimed in this study to evaluate the association of this GALNT2 rs4846914 variant with metabolic traits, including the obesity traits and related biomarkers, such as Apolipoproteins and ANGPTL3, in a cohort of Arab individuals." (PMID 35885984, 2022). "A recent study showed an association of the GALNT2 rs4846914 variant with atherogenic index in overweight/obese women with gestational diabetes mellitus, thus highlighting the possible regulatory role of GALNT2 in obesity and lipid traits." (PMID 35885984, 2022). "The study points out that the G allele at the GALNT2 rs4846914 coordinates the regulation of body fat, levels of HDL, and apolipoproteins in mediating obesity." (PMID 35885984, 2022). "It is also recognized that GALNT2 is a novel modulator of adipogenesis and related cellular phenotypes, thus becoming a potential target for tackling the epidemics of obesity and its devastating health consequences." (PMID 35885984, 2022). "In this study, we evaluated the association between GALNT2 rs4846914 variant, known for its association with lipid levels in European cohorts, with plasma levels of ANGPTL proteins, apolipoproteins, lipids, and obesity traits in individuals of Arab ethnicity." (PMID 35885984, 2022). "Assessment for frequency difference between obese vs non-obese individuals demonstrated association of the GALNT2 rs4846914_G allele with an increased risk of obesity at an odds ratio of 1.47 (CI:1.024–2.055) with p-value 0.03." (PMID 35885984, 2022). "The fact the LPS downregulates GALNT2, suggests it could play a role during the development of dysfunctional adipose tissue as seen in obesity." (PMID 27438462, 2016).